CXCL9 (C-X-C motif chemokine ligand 9)
Diseases named in the same sentence as CXCL9 in open-access papers (continued):
Sharing a sentence is not in itself a finding about the gene and the disease.
tumor (continued). "In sum, our model uniquely integrates SEMA6D-mediated immune evasion and CXCL9-driven anti-tumor immunity, offering a bi-directional molecular framework to refine risk stratification and boost ICI efficacy." (PMID 41438751, 2025). "Using animal and human models of MMRd, we determined that interactions between MHC+ C1Q+ CXCL9+ macrophages and TCF+ BHLHE40+ PRF1+ T cell subsets are associated with control of MMRd tumor growth, during anti-PD-1 treatment." (PMID 40027748, 2025). "Despite these factors, we found that lung macrophages isolated from lung biopsies taken at sites distant from the tumor exhibited corticosteroid sensitivity, as evidenced by reduced expression of CXCL9, CXCL10, and CXCL11." (PMID 41229420, 2025). "The HDAC inhibitor, 2-hexyl-4-pentylene acid (HPTA), demonstrated significant anti-tumor effects in a rat breast cancer model by leading to the increase in CXCL9/10 mRNA expression and protein levels following treatment." (PMID 40040700, 2025). "Cluster 10 expressed high levels of Cxcl9 and Cxcl10, which encode for the eponymous chemokines that are important for the recruitment and spatial localisation of CD8+ T cells in tumours." (PMID 40745918, 2025). "Meanwhile, protective gene of our model, CXCL9 regulates immune cell migration, differentiation, and activation, leading to tumor suppression." (PMID 41438751, 2025). "It is intriguing that Cxcl9 emerged as one of the most downregulated genes in tumor cells from both GeoMx and snRNA-seq, indicating a potential critical role of Cxcl9 and Cxcl10 in the observed phenotypes." (PMID 41332581, 2025). "Elevated levels of CXCL9, CXCL10, and CXCL11 in ascitic fluid facilitate NK cell trafficking to tumor sites and are associated with impaired tumor progression." (PMID 41567203, 2025). "The tumor-infiltrating GZMB+CD8+ T cells were spatially adjacent to CXCL9+CD68+ macrophages, which were positively correlated." (PMID 41321309, 2025). "In sum, we conclude the suppression of Cxcl9 and Cxcl10 in old tumors drives decreased infiltration of anti-tumor T cells and faster growth of the tumor." (PMID 41332581, 2025). "Untransformed mammary ducts from the same slides didn’t express Cxcl9/10, indicating the expression in young is largely tumor specific." (PMID 41332581, 2025). "High tumor mutational burden (TMB) often correlates with elevated neoantigen load and IFN-γ production, leading to upregulation of CXCL9/10 and increased TIL recruitment." (PMID 40475782, 2025). "The prevailing theory suggests that CXCL9 is crucial in mediating lymphocyte infiltration into specific tumor sites while concurrently inhibiting tumor progression." (PMID 40909948, 2025). "The reprogramming enhances cytotoxic T cell-mediated anti-tumor responses in a CXCL9-dependent manner." (PMID 41417432, 2025). "Tumor-infiltration of CXCL9+ macrophages and B cells correlates with a better response to immune checkpoint blockades (ICBs) 30,61,62." (PMID 40883281, 2025). "Above all, these results indicated that the CCL2/8-CCR2 axis and CXCL9/10-CXCR3 axis were involved in the anti-tumor immunity of the TTFields and anti-PD-1 treatment." (PMID 40098106, 2025). "TTFields enhance the effectiveness of anti-PD immunotherapy by improving CD4+ T cells and CD8+ T infiltration via inducing ICD to increase CCL2/8 and CXCL9/CXCL10 expression of tumor cells." (PMID 40098106, 2025). "This leads to enhanced anti-tumor activity by cytotoxic T cells, which is dependent on the chemokine (C-X-C motif) ligand 9 (CXCL9)." (PMID 41373839, 2025). "This signaling pathway promotes tumor progression by suppressing CD8+ cytotoxic T lymphocyte infiltration through inhibition of CXCL9 production in TAMs, a chemokine crucial for recruiting cytotoxic T cells." (PMID 41300283, 2025).
tumor (continued). "Spatial and deconvolution analyses reveal that CXCL9+ TAMs preferentially localized to the tumor periphery, whereas SPP1+ TAMs accumulated in the tumor core and were associated with advanced disease stages and worse overall survival in multiple cohorts." (PMID 40725473, 2025). "TTI-101 treatment decreased pY-STAT3 expression in tumors with accompanying increases in several NF-κB anti-tumor target genes including CXCL9, a chemokine for primed T cells." (PMID 40356899, 2025). "CXCL9, -10, -11 are CXCR3 ligands, expressed by several different cells within a tumor, that recruit T-cells and NK cells, with CXCL9 and 10 primarily recruiting activated CD4+ and CD8+ effector cells and CXCL11 recruiting or promoting development of T-regs." (PMID 40176808, 2025). "Intriguingly, these cells can exert anti-tumor effects by releasing mediators such as CXCL9, CXCL10, TNF-α, granzyme, cationic proteins, in melanoma, CRC, and HCC." (PMID 40380196, 2025). "Results showed that upon cytokine stimulation most of the studied genes were expressed at a lower level in the tumor cells than in control cells, such as Stat1, Irf1, Cxcl9, Cxcl10, IκBα, and Bcl2 (p< 0.05)." (PMID 40287766, 2025). "For example, the imbalance between chemokine receptor CXCR3 expressed by TILs that traffic CTL to the TME and CXCL9/CXCL10 (ligands of CXCR3) up-regulated by tumor cells leads to inefficient recruitment of CTL to the tumor." (PMID 40292310, 2025). "This study confirms that SFV increases the expression of T-cell chemoattractant genes Cxcl9, Cxcl10, Cxcl11 and immune checkpoint molecule gene Cd40, promoting anti-tumour immunity." (PMID 40547518, 2025). "Concurrently, ADM can induce TREM2+ TAMs to release Galectin-1, reducing CXCL9 production thereby inhibiting CD8+ T cell tumor recruitment." (PMID 41450464, 2025). "One cluster termed Triple‐I with the best patient survival showed the highest number of tumor infiltrating lymphocytes along with 22 overexpressed genes, including CXCL9 and AIM2." (PMID 40492347, 2025). "In this study, we showed that inflammatory monocytes, which in human tumours correspond to CXCL9+CXCL10+ macrophages, drive T cell restimulation in the TME." (PMID 39604727, 2025). "Some of them, such as CCL5, CXCL10, and CXCL9, are produced by DCs upon activation to favor tumor T cell recruitment." (PMID 40578365, 2025). "This is consistent with the increased expression of Cxcl9/10 observed in young tumor cells by GeoMx, snRNA-seq and RNA-scope." (PMID 41332581, 2025). "CXCL9, therefore, can either promote or inhibit tumor progression by influencing the tumor microenvironment." (PMID 40362215, 2025). "We found that THP1-derived macrophages (THP1-MΦ) cocultured with IFN-β–treated USP5-deficient tumor cells exhibited upregulated ISG15, IFI44, CXCL9, and CXCL10 mRNA expression." (PMID 41321309, 2025). "GPR182, a scavenger of CXCL9/10, impairs lymphocyte recruitment and contributes to immunotherapy resistance, representing a promising target for cold tumours." (PMID 40361472, 2025). "Future studies comparing tumour models and time points will help clarify the overlap between MHCII+CCR7neg and Cxcl9 cDC1s, as well as their localisation within tumours." (PMID 40745918, 2025). "Innate immune cells, such as mature dendritic cells and M1-tumor-associated macrophages (TAM), produce cytokines (IFN-α, IL-12, IL-18, or TNF-α) and chemokines (CXCL9, CXCL10, or CCL21) that suppress tumor angiogenesis." (PMID 41373757, 2025). "The interplay of the tumor-derived molecules like immune checkpoint ligands (PD-L1 and PD-L2), chemokines (CXCL9, CXCL10, and CXCL12), along with cytokines (TGF-β and IL-10), creates a complex immunosuppressive environment in EwS." (PMID 40242222, 2025). "Given this potential functional significance, we next set out to validate the expression of Cxcl9/10 by RNAscope at the RNA-level and ELISA at the protein level, to confirm that Cxcl9/10 are downregulated in old tumor cells." (PMID 41332581, 2025).
tumor (continued). "From snRNA-seq global clustering, Cxcl10+ and Cxcl9+ cells were enriched in a subset of the tumor cluster and an adjacent subset of luminal AV cluster in the young." (PMID 41332581, 2025). "These are all known factors that can enhance T cell‐mediated anti‐tumor immunity as Cxcl9 and Ccl5 are chemoattractive to T cells, and IL‐12 is a potent activator of CD8 T cell effector functions." (PMID 39639496, 2025). "In sum, our results suggest that Cxcl9 and Il12b cDC1s are enriched in different regions of the tumour, with Cxcl9 cDC1s preferentially located in the parenchyma and the Il12b cDC1s in tumour border regions." (PMID 40745918, 2025). "Clinical trial NCT04830592 uses intravenous infusion to deliver an adenoviral vector producing a bispecific T cell activator (TAc) plus CXCL9/CXCL10/IFNa2 to kill tumor cells and stimulate immunity against the tumor cells." (PMID 41332581, 2025). "We found that Cxcl9 and Il12b cDC1s were enriched in different regions of the tumour: Cxcl9 cDC1s were overrepresented in the parenchyma of the tumour, while Il12b cDC1s were located preferentially at the border of the tumour." (PMID 40745918, 2025). "CXCL9/-10/-11 expression in OPC tumor biopsies compared to clinically normal tissue correlated with patient outcome." (PMID 40176808, 2025). "The traditional model of T cell recruitment mediated by tumor cell-secreted chemokines such as MIG (CXCL9) and IP-10 has been expanded to include the role of metabolic reprogramming in regulating T cell migration." (PMID 40124373, 2025). "Genetically engineered macrophages carrying an oncolytic adenovirus were developed to maintain an anti-tumoral-like phenotype and deliver interleukin-12 and CXCL9 directly to local tumor sites, thereby reversing the immunosuppressive TME." (PMID 41417432, 2025). "In our model, CXCL9/10 expression was detected in both tumor and immune cells, with tumor cells being the predominant source, as supported by GeoMx, RNAscope, and snRNA-seq analyses." (PMID 41332581, 2025). "Preclinical administration of CXCL9/10 enhances T-cell recruitment and suppresses tumour growth, although clinical translation remains challenging." (PMID 40361472, 2025). "In melanoma models lacking COX1/COX2 (Ptgs1−/−Ptgs2−/−), and thus PGE2, MHCIIhiCCR7neg cDC1s retain high levels of IL‐12 and CXCL9, allowing them to cluster with tumor‐specific CD8+ T cells, promoting their activation and driving local immune control." (PMID 40667699, 2025). "CXCR3, the cognate receptor for CXCL9, −10, −11, is predominantly expressed on monocytes as well as T, natural killer (NK), dendritic, and tumor cells." (PMID 40447617, 2025). "Delivery of indole-3-acetic acid by tumor-colonizing bacteria changes the tumor microenvironment in a murine model, significantly increasing levels of CXCL9 and IFN-γ and elevating tumor-infiltrating T-cell abundance and activation." (PMID 40055466, 2025). "On the one hand, CXCL9/CXCR3 promotes anti‐tumor immunity by attracting CXCR3+ cytotoxic lymphocytes to the tumor microenvironment, which can inhibit tumor growth." (PMID 40145607, 2025). "At the same time, IκBζ simultaneously repressed several other chemokines, known to regulate recruitment of T cells and NK cells into the tumor microenvironment, such as CXCL9, CXCL10, and CCL546." (PMID 40562773, 2025). "C5aR deficiency or inhibition restored TAMs to an anti-tumor function by enhancing CD8+ cytotoxic T cell responses, dependent on CXCL9 secretion from TAMs." (PMID 41300283, 2025). "Several ISGs such as GBP family genes Gbp4 and Gbp5, Cxcl9, Oas2, and Stat1, were significantly downregulated in the old Tumor-3 subcluster." (PMID 41332581, 2025). "The expanded NK cells express the chemokine receptors CXCR3, CCR5, and CXCR6, and the lung of tumor-resected mice express mRNA of the corresponding ligands CXCL9/10/11, CCL3/4/5, and CXCL16." (PMID 39835538, 2025).
tumor (continued). "Since TAMs are partially derived from monocytes recruited to the tumor, we examined the role of PU.1 in expression of CXCL9 in BMDMs stimulated with 100 ng/mL lipopolysaccharide (LPS) for 5 h." (PMID 40867314, 2025). "mIHC staining confirmed the presence of IFN‐Mac_CXCL9 and Angio‐Mac infiltration in tumours, indicated by the co‐localisation of their gene signatures." (PMID 41275425, 2025). "In the current study, we revealed that tumor-infiltrating CXCL9+ macrophages are one of the most important responders to IFN-I." (PMID 41321309, 2025). "Re‐polarizing the tumor macrophages to T cell supporting phenotypes (secreting Ccl5, Cxcl9, and IL‐12) promotes T cell stimulation and adaptive immune recognition of tumors." (PMID 39639496, 2025). "To investigate this relationship globally and at Cxcl9/10 genes in young and old tumor cells, we performed snATAC-seq and snRNA-seq in parallel on the same nucleus preparation." (PMID 41332581, 2025). "Chemokines such as CXCL9 are recognized for their potent capacity to recruit T lymphocytes, thereby activating and sustaining robust anti-tumor immune responses." (PMID 40557143, 2025). "CXCL9 and CXCL10, chemokines highly expressed in M1-type TAMs, especially those associated with inflammation, promote T cell recruitment, boosting anti-tumor immune responses, and are often observed in patients who respond well to immune checkpoint inhibitors." (PMID 40055311, 2025). "ELISA on young and old mammary gland whole tissue homogenate two weeks after tumor induction showed that the protein level of CXCL9/10 was also significantly higher in young tumors than in old." (PMID 41332581, 2025). "Compared to administering free CXCL9 and dBET6, the nChap platform improves pharmacokinetics, increases tumor accumulation, reduces systemic toxicity, and extends circulation time." (PMID 40284496, 2025). "Cxcl9 and cCxcl10 play a crucial role in the recruitment of cytotoxic CD8 + T cell and Th1 CD4 + T cell into the tumour site, and are generally associated with better prognosis and enhanced response to Immunotherapy." (PMID 40316725, 2025). "Targeted interventions showed that decreased expression of Cxcl9/10 is responsible for reduced T cell infiltration and weakened anti-tumor immunity." (PMID 41332581, 2025). "IFN‐primed macrophages, specifically IFN‐Mac_CXCL9, accumulated significantly in tumour samples, prompting further analysis." (PMID 41275425, 2025). "For instance, CXCL9/10 secreted by DC1s establish chemotactic gradients that guide CXCR3+ CD8+ T cells to tumor niches, while their co-expression with CCL5 amplifies T cell infiltration and correlates with improved survival in solid tumors." (PMID 40698080, 2025). "Increased levels of the Th1 chemokines C-C motif chemokine ligand 5 (CCL5), CXC-chemokine ligand 9 (CXCL9) and CXCL10 are associated with increased numbers of tumor-infiltrating CD8+ T cells." (PMID 40959109, 2025). "Dense clusters of mDCs, forming compact aggregates within the tumor epithelium, characterize regressing lesions and create CXCL9+/CXCL10+ chemokine-rich niches and local T cell enrichment." (PMID 41279770, 2025). "Endothelial cells from Kmt2c KO and Kmt2d KO tumours were distinct from the WT and shared top upregulated genes, including Cd74, Cxcl9, H2-Ab1 and H2-Eb2." (PMID 38926506, 2024). "RT-qPCR was employed to detect the mRNA levels of these chemokines in tumor tissues of our exercise models, confirming that Ccl5, Cxcl10, Cxcl9, and Cxcl11 were significantly increased in Ex mice compared to the Ctrl group." (PMID 38622609, 2024). "CXCL9 and CXCL10 mediated accumulation of CD8+ T cells in tumors occurs following checkpoint blockade and these IFNγ-dependent events are mediated by tumor-associated macrophages." (PMID 38786066, 2024). "For example, a CXCL9 monokine induced by interferon-γ (MIG) is produced during inflammatory conditions by myeloid cells within the tumor microenvironment." (PMID 39451257, 2024).
tumor (continued). "Dendritic cells must reach the tumour first in order to generate chemokines, such as CXCL9 and CXCL10, which recruit effector T cells to the tumour, resulting in tumour control." (PMID 38481668, 2024). "In vitro, CXCL9 production by TADCs increased PD-L1 expression on BCa T24 cells, thereby inhibiting anti-tumor T cell responses and promoting tumor growth." (PMID 39409924, 2024). "We examine AAV delivered CXCL9 transgene tropism, durability, and impact on lymphocyte tumor migration." (PMID 38997283, 2024). "The functions of CXCL9 are multifaceted, encompassing not only the behaviors of immune cells but also their interactions with tumor cells." (PMID 38791448, 2024). "SRC-3 KO in Tregs results in increased infiltration of cytotoxic immune cells into the tumor and elevated levels of IFNγ and CXCL9 in the TME." (PMID 38698860, 2024). "For example, CCL5 produced by tumor cells or CXCL9 and CXCL10 also expressed by tumor-resident myeloid cells determine effector T-cell recruitment to the tumor microenvironment." (PMID 39669575, 2024). "Within the combination treatment groups of anti-PD-1 and carbo/pax, the cytokines positively correlating with tumor burden were G-CSF (0.84700, p = 0.0334), IL-9 (r = 0.8174, p = 0.0470), and CXCL9, also known as MIG (r = 0.9072, p = 0.0125)." (PMID 39623404, 2024). "Th1 cells express CXCR3, and lack of CXCR3 expression on Th2 cells suggests that the enrichment of these cells in the tumor is possibly due to an indirect effect of CXCL9/10 that alters the soluble milieu of the TME." (PMID 38518770, 2024). "The qRT−PCR analysis revealed that upregulated expression of CTSC, CDCA8, and G6PD, whereas downregulated expression of CXCL9 in HCC compared with adjacent tumor tissue and normal liver cell lines." (PMID 38742112, 2024). "CXCL9 overexpression reduced T cells in immunological organs and the tumor microenvironment, promoting PCa development." (PMID 38745115, 2024). "Focusing on the CD20+ tumor cells, the transcriptomic analysis showed that CXCL9 was most important for the classification of patients with either high or low TC,57+ infiltration." (PMID 39001353, 2024). "The combination of CXCL9/10-DC and anti-PD-1 or anti-PD-L1 elicited robust tumor regression, resulting in complete eradication of tumors in ∼30% of the mice." (PMID 38518770, 2024). "Remarkably, within 24 to 48 h postinfusion of CANDI400, we observed a considerable induction of CXCL9 throughout the tumor." (PMID 38342608, 2024). "Further exploration of the role of CXCL9 in the tumor microenvironment reveals its involvement in various processes such as angiogenesis, metastasis, and inflammatory response." (PMID 38791448, 2024). "CXCL9 is a member of the ELR-negative CXC chemokine subfamily that is activated by interferon-γ (IFN-γ) and released by tumor-associated dendritic cells." (PMID 38590525, 2024). "CXCL9 is a chemokine primarily secreted by monocytes, endothelial cells, fibroblasts, and tumor cells, with pleiotropic roles across various cancers including TNBC." (PMID 39695149, 2024). "A previous study found that CXCL9 expression enhances T-cell infiltration and suppresses tumor growth." (PMID 38931345, 2024). "In the immune microenvironment, high expression of CXCL9 in the tumor core or/and invasive margin were closely related to and should be considered as independent protective factors of prognosis." (PMID 38957805, 2024). "Tumor cells secrete Shh to drive TAMs to polarize towards M2, and the production of CXCL9 and CXCL10 by polarized TAMs is inhibited." (PMID 39372416, 2024). "In conclusion, systemic administration of either CXCL9-Fc or CXCL10-Fc markedly increases the relative number of activated highly potent tumor-specific CD8+ T cells at the tumor site, and to some extent PD-1 expression on about 7-10% of these cells." (PMID 39474427, 2024). "First among these were CXCL9 and CXCL10, both of which have been linked to enhanced CAR T cell anti-tumor activity." (PMID 39566469, 2024).